MTOR (mechanistic target of rapamycin kinase)
Diseases named in the same sentence as MTOR in open-access papers (continued):
Sharing a sentence is not in itself a finding about the gene and the disease.
cancer (continued). "However, male patients who received rapamycin in post-transplantation and cancer therapies have a high prevalence of infertility, suggesting a critical role of mTOR signaling in spermatogenesis." (PMID 30636722, 2019). "We assessed the effects of an Akt1/2 inhibitor and the mTOR inhibitor, everolimus, which is a Food and Drug Administration-licensed drug for use in a number of cancers and acts on the Akt pathway, on pAkt and proliferation responses in cells expressing the WT PRLR and mutant Asn492Ile PRLR." (PMID 30445560, 2019). "Many PTK inhibitors block cancer cell proliferation by inhibiting the Akt/mTOR signaling pathway." (PMID 30959969, 2019). "This acute response may override the neuronal PI3K/Akt/mTOR activation, with the goal of reducing energy stress and oxidative damage, until the patient either dies or survives from the cancer." (PMID 30881282, 2019). "(iii) a third mechanism by which PA might play a role in cancer biology is through its ability to bind to and influence the mammalian target of rapamycin (mTOR), a key regulator of cell proliferation and growth." (PMID 31231646, 2019). "Interestingly, the theory of insensitivity to mTOR in the face to the hypoxic condition is consistent with acidic pH microenvironment of cancer cells." (PMID 31557936, 2019). "In addition, the Akt/mTOR pathway and apoptosis also participate in cisplatin resistance in various cancers." (PMID 31475112, 2019). "In turn, extracellular lactate is associated with malignant transformation and can regulate cancer-related signaling pathways (e.g., NF-kB/IL-8, HIF1, and PI3K/Akt/mTOR/Bcl-2), angiogenesis, and ATP production, which in turn influence cell proliferation and migration." (PMID 30967136, 2019). "Although the literature reports contradictory prognostic values of PIK3CA in aggressive cancers, most of the available data highlight the important role of PIK3CA mutation in mediating tumorigenesis via increased signaling of the PI3K/AKT/mTOR survival pathway." (PMID 31905960, 2019). "Understanding mTOR activities in cancer is the basis to develop new antitumor therapy strategies." (PMID 31766386, 2019). "Recently, mTOR has been found to control cancer, inflammatory, and neuropathic pain." (PMID 30032425, 2019). "mTOR is often considered a downstream effector of numerous mutant oncogene pathways, such as the PI3K/Akt pathway and the Ras/Raf/Mek/Erk (MAPK) pathway, causing overactivation of mTOR and hence cancer." (PMID 31007702, 2019). "The Akt/mTOR pathway plays significant roles in the regulation of autophagy, as well as cancer cell growth and proliferation; inhibition of this pathway has activatory roles in the autophagy pathway and inhibitory roles on cancer cell proliferation." (PMID 30669284, 2019). "Discussing the role of the mTOR pathway in the immune system, cancer, and bone metabolism could help to explore the mechanism of action of novel potential therapeutic agents for which further investigation is needed." (PMID 31766386, 2019). "Therefore, mEAK-7 forms an alternative mTOR complex with DNA-PKcs to regulate S6K2 in human cancer cells." (PMID 31288154, 2019). "PI3K/Akt/mTOR role in cell cycle initiation is not the only shared pathological mechanism between AD and cancer, underlying neurodegeneration in AD." (PMID 30881282, 2019). "The PI3K/Akt/mTOR pathway, an important cancer-promoting signalling cascade that regulates numerous biological functions, such as cell proliferation and migration, is activated in many types of human cancers, including HCC47." (PMID 31754201, 2019). "This hypothesis was further supported by the finding that R2 cells lost the expression of EIF4B, a substrate of the mTOR pathway, required for cell proliferation and survival of cancer cells." (PMID 31013771, 2019). "The central role of mTOR in metabolic rewiring makes it a promising target for cancer therapy." (PMID 31817676, 2019).
cancer (continued). "Together with Akt, mTor (kinase) interfered in the control of cancer cell growth and proliferation." (PMID 31590362, 2019). "mTOR inhibitors have shown promising anti-cancer effects in HPV-positive HNSCC mouse models." (PMID 30970654, 2019). "ATF6 induces the expression of RHEB, which activates mTOR signaling and renders therapeutic resistance to dormant cancer cells, suggesting targeting ATF6 might be one of the valuable therapeutic strategies." (PMID 31739582, 2019). "Furthermore, our results display a time‐dependent in vitro effect of PC1 on mTOR signalling in cancer cells." (PMID 31251475, 2019). "Although not high rate of PIK3CA activating mutations, immunohistochemical evaluation of downstream PIK3CA targets EIF4E and 4E-BP1 suggests that additional mechanisms may play positively regulation in mTOR pathway in cancers." (PMID 30682771, 2019). "Moreover, we independently demonstrated that mTOR signaling was enhanced in X60 radioresistant cancer cells as compared with parental NR-S1 cells, whereas rapamycin treatment decreased their radioresistant phenotype." (PMID 31799186, 2019). "The only modest, yet proven, efficacy of mTOR inhibitors for the treatment of various types of cancer may thus be the result of a delicate balance of these effects." (PMID 31058807, 2019). "However, Ag-NPs have also been shown to trigger cytotoxic autophagy in non-cancer murine pro-B cells (Ba/F3) through the modulation of PI3K/mTOR signaling pathway along with generation of ROS and release of silver ions." (PMID 30483817, 2019). "Interestingly, PI3K/Akt/mTOR acts as a cross point between AD and cancer, as this pathway is activated under the influence of stress-related hormones, causing cell proliferation and autophagy reduction." (PMID 30881282, 2019). "However, despite a significant efficacy in pre-clinical models, the clinical tumor response to mTOR inhibitors is relatively modest because the compounds have only limited efficacy as single agents in cancer therapy." (PMID 30642006, 2019). "Emerging evidence demonstrates that mTOR signaling is a crucial regulator of cancer progression." (PMID 31724536, 2019). "mTOR is a major target for treatment human diseases including cancer." (PMID 31519156, 2019). "Therefore, loss of PTEN and/or mutations of PIK3CA result in constitutive activation of Akt/mTOR, which have been documented in various cancers." (PMID 31370278, 2019). "In addition, the activation of the PI3K-pAkt-mTOR pathway triggered by IL-6 was shown to be related to cell proliferation and metastasis in a variety of cancers." (PMID 31252615, 2019). "If this is true, further identification of small molecules to disrupt CTPS polymerization may be a promising strategy for combating mTOR-driven cancers." (PMID 30857853, 2019). "The PI3K/AKT/mTOR pathway is a survival pathway constitutively activated in many types of cancer." (PMID 31839828, 2019). "Next, we sought to investigate whether this GLI1 regulation by PI3Kα/mTOR is also evident in other HH-driven paediatric cancers." (PMID 31492956, 2019). "Inhibition of the rate-limiting enzyme in guanylate nucleotide synthesis, inosine monophosphate dehydrogenase (IMPDH), selectively kills mTORC1-activated cancer cells, implying that targeting nucleotide metabolism is promising for treating tumors with elevated mTOR signaling." (PMID 30857853, 2019). "Therefore, the combination of autophagy inhibitors and PI3K/AKT/mTOR pathway inhibitors will make more sense in cancer treatment." (PMID 31835352, 2019). "Furthermore, ZBM-H effectively inhibited tumor cell growth in vitro and in vivo via stimulating AMPK/mTOR dependent autophagy and apoptosis, thereby providing new evidence for the function of endogenous HOCl-modified proteins regulating cancer cell growth." (PMID 31719525, 2019). "Furthermore, AMPK inhibits IRS1 mediated IR and IGFR oncogenic signaling via PI3K/Akt/mTOR, which, potentially, also contributes to the anti-cancer effect of metformin." (PMID 31835318, 2019).
cancer (continued). "It should be noted that the conclusions on whether the mTOR cascade is activated or inhibited in cancer cells after changes in PC1 function are based only on the phosphorylation of a single mTOR‐related protein." (PMID 31251475, 2019). "Due to the characteristic of each cell, this phenomenon (that uses different mechanisms of chemoresistance acquisition in cancer cells) is induced by signal transduction proteins such as Akt, mTOR, ERK, p38, SHH, and Wnt, depending on the activity or expression level of kinases." (PMID 31658599, 2019). "The aberrant activation of mTOR enhances the tumorigenesis of cancer cells." (PMID 31724536, 2019). "Moreover, both rapamycin and disruption of mTOR extended the lifespan of mice, indicating the important role of MTOR in senescence, cancer, and aging." (PMID 31219803, 2019). "The PIK3/ Akt/ mTOR pathway plays a key role in various cancers and among them thymic tumors." (PMID 30897085, 2019). "Because multiple mutant genes are directly associated with the oncogenic activation of the mTOR pathway, it is not surprising that multiple clinical trials are currently targeting aberrant mTOR signalling in cancer." (PMID 30970654, 2019). "Similarly, curcumin was found to modulate the Akt/mTOR pathway, leading to the reduction of cancer cell proliferation." (PMID 31159487, 2019). "Data from organ transplant recipients show that longterm immunosuppressive regimens which include mTOR inhibitors are associated with an overall reduced cancer risk when compared to patients not treated with mTOR inhibitors." (PMID 30787878, 2019). "In addition to facilitating the transport of EAAs for protein synthesis, LAT1 and ASCT2 stimulate the growth of cancer cells via mTOR." (PMID 30871192, 2019). "Also, this is believed to be among the causes responsible for the modest clinical efficacy shown by mTOR inhibitors in cancer treatments." (PMID 31464606, 2019). "Of note, Akt-mTOR pathway has been indicated as a metabolic regulatory center of cancer." (PMID 31137633, 2019). "Moreover, the C‐dots disrupt likely through nucleotide excision DNA repair at low dose during DNA ligation step suggesting the antimicrobial effect and targeting Pim‐1, EGFR, mTOR, and DNA damage pathways in cancer cells." (PMID 31692950, 2019). "Moreover, alterations in the PI3K/AKT/mTOR pathway, e.g., PTEN loss, have an impact on cell energy metabolism and the metabolic reprogramming of cancer cells is another important hallmark of cancer." (PMID 31500143, 2019). "Therefore, autophagy inducers such as the mTOR inhibitors have also been considered as potential cancer treatments." (PMID 31057611, 2019). "Prior studies have shown that the mevalonate pathway in cancer cells can impact cell division, tumor growth, and metastatic potential and modulate immune response and mTOR signaling." (PMID 31225926, 2019). "Previous data has shown that mTOR inhibitors in conjunction with Src inhibitors are more efficacious in treating various cancer types, we therefore considered whether this mechanism was functional in A52 cells." (PMID 30794695, 2019). "However, application of mTOR inhibitors in cancer therapy is concerning because of their potential toxicity." (PMID 31595162, 2019). "However other studies have shown that phosphocholine content of cancer cells isn’t consistently altered by treatment with PI3K/Akt/mTOR inhibitors." (PMID 30056610, 2019). "Although PIK3CA-mutated cancer is usually sensitive to mTOR inhibition, activation of GSK3β in response to PI3K/mTOR inhibition may lead to the resistance to PI3K/mTOR inhibitors in PIK3CA-mutated cancer." (PMID 31277692, 2019). "Sustained mTOR signaling drives resistance to targeted therapeutics in cancer treatment." (PMID 31388935, 2019). "This may be why mTOR activity is often elevated in cancer cells; the rationale behind its use as an anti-cancer drug." (PMID 31136303, 2019).
cancer (continued). "Accumulating evidence suggests that PI3K/Akt/mTOR signaling is involved in the resistance to many cancer therapies, including chemotherapy, RTK inhibitors, anti-angiogenic therapy, mitogen-activated protein kinase (MAPK) pathway inhibitors, hedgehog pathway inhibitors, and immunotherapy." (PMID 31262325, 2019). "We have also noted that the efficacy of metformin, with respect to decreasing TNBC cell proliferation, increasing apoptosis and inhibiting the mTOR pathway (pro-survival and protein synthesis pathway activated in cancer cells), significantly increased under zero glucose/glucose-starved conditions." (PMID 30626087, 2019). "The PTEN/PI3K/mTOR pathway is one of the main focuses in cancer discovery because of the frequent dysregulation through the increased expression and/or activation of receptor tyrosine kinases, mutations in pathway components, or loss of negative pathway regulators, such as PTEN." (PMID 31416195, 2019). "This review focuses on targeting mTOR inhibitors in PDT of cancer cells." (PMID 31075885, 2019). "As examples, the role of phosphoinositide 3 kinase/Akt/ mammalian target of rapamycin (PI3K/Akt/mTOR) signaling pathway in cell cycle re-entry and blocking autophagy are discussed as potential common intracellular components between AD and cancer pathogenesis, with diverse clinical diagnosis." (PMID 30881282, 2019). "In addition, proteomic analysis showed the effectiveness of miR‐126 action on the mTOR pathway, one of the key controllers of cancer metabolism." (PMID 31115969, 2019). "The cellular metabolism mediated by mTOR is involved in the connections between cancer cells and tumor microenvironment during cancer advance and drug resistance acquisition, indicating the potential benefits of PI3K-Akt (protein kinase B)-mTOR pathway blockage." (PMID 30987378, 2019). "Similarly, we and others have reported that Cur is a potent inhibitor for the PI3K/Akt/mTOR pathway in diverse types of cancers, including GB." (PMID 31841506, 2019). "Other processes altered under diabetic conditions point to a regulation of carcinogenesis, as the epidermal growth factor receptor (ErbB) and the PI3K–Akt signaling pathways, both in the upstream cascade of mTOR, and regulators of proliferation in several cancers including CC." (PMID 30628165, 2019). "Given the complexity in targeting the PI3K signaling pathway in cancer, our results also demonstrate that a strategy to target mTOR and PI3K kinase by using a dual inhibitor results in better effects in combination with Palbociclib than the combination of other inhibitors in this pathway." (PMID 31331377, 2019). "mTOR is not only an important cancer-related pathway, but also crucial for hematopoietic cell fate, since the differentiation of naive T-cells into distinct effector T-cells is promoted by mTOR." (PMID 34484811, 2019). "As reported, mTOR is aberrantly overactivated in more than 70% of cancers." (PMID 30754640, 2019). "Previous reports have shown that brevilin A could inhibit the PI3K/AKT/mTOR pathway to induce apoptosis and autophagy in multiple cancer types." (PMID 31108969, 2019). "Inhibition of both PI3K and mTOR ought be effective in eliminating cancer cells." (PMID 31921637, 2019). "Given the different subunits and substrates of the two mTOR complexes, it is increasingly recognized that these complexes are distinct in their physiological roles and have different consequences to their activation and dysregulation in cancer." (PMID 31393061, 2019). "The acidic protein tuftelin 1 (TUFT1) is involved in mTORC1 activation by interacting with the RAB GTPase activating protein 1 (RABGAP1) and therefore may constitute a biomarker or a candidate for targeted therapy in mTOR activated, progressive cancers." (PMID 31261735, 2019). "In addition, one of the approaches that RAC1 uses to control cancer cell metabolism is by interacting with mTOR." (PMID 31314174, 2019).
cancer (continued). "The activation of HIF pathway in these cells was shown to be essential for induction of PI3K, AKT, mTOR pathway which plays a critical role for cancer stem cell quiescence and maintenance by attenuating cancer stem cell metabolism and growth via mTOR and promoting cell survival by AKT signaling." (PMID 31366128, 2019). "However, mTOR inhibition in cancer, especially as monotherapy, has limited benefits, increasing survival by just few months, and several studies demonstrated the occurrence of drug resistance." (PMID 31627299, 2019). "The repetitive metabolic stress is a shared phenomenon for both AD and cancer, which could trigger PI3K/Akt/mTOR activation, cell cycle re-entry and autophagy inhibition, the other three shared features between AD and cancer." (PMID 30881282, 2019). "Moreover, genetic aberrations in components of mTOR complexes are reported to have a close relationship with cancer." (PMID 30754640, 2019). "Reactivation of T-cell function via activation of mTOR may overcome the tumor immune escape and beneficially complement an anti-cancer therapy." (PMID 31417567, 2019). "AMPK-mediated autophagy and Akt/mTOR pathways play important roles in current cancer treatments." (PMID 31475112, 2019). "Moreover, VCP/p97 expression correlated with several processes that are linked to cellular metabolism and are frequently deregulated in cancer, such as ‘mTOR signalling pathway’ and ‘MAPK signalling pathway’." (PMID 30626938, 2019). "It warrants further studies to clarify which cancer-associated mutations in raptor, rictor, and RHEB may be associated with mTOR inhibitors resistance." (PMID 31277692, 2019). "Due to the critical role that mTOR plays in cell growth and metabolism and availability of the natural compound, rapamycin, to inhibit its activity, there are numerous ongoing efforts to target the mTOR signaling pathway for cancer therapy." (PMID 31817676, 2019). "Recent studies suggest that rapamycin, which regulates mTOR and its downstream effectors, could diminish chronic inflammatory, neuropathic, and cancer pain." (PMID 30032425, 2019). "It has been reported that dysregulation of the Akt/mTOR pathway plays a key role in the initiation and progression of different forms of cancer and, therefore, we studied the effects of treatment with 2DG, metformin and their combination on the Akt/mTOR pathway in MMECs." (PMID 31698699, 2019). "Considering the crucial role of PI3K/mTOR/Akt signaling in cancer initiation, progression and metastatization, some inhibitors of this pathway have been tested and afterwards included in the therapeutic strategy of various cancer types." (PMID 31404976, 2019). "Studies have demonstrated that suppression of the PI3k/AKT/mTOR pathway by an mTOR inhibitor may inhibit cancer cell invasion and migration and promote apoptosis in tumors, while PI3K signaling is known to contribute to the advancement of cancer." (PMID 31783709, 2019). "Pathways including glutathione metabolism, wnt signaling, central carbon metabolism in cancer, mTOR signaling, pancreatic secretion, protein and fat digestion, insulin secretion, and salivary secretion might be closely related with CCA development." (PMID 31687280, 2019). "mTOR is also vital in advanced cancer development and metastatic cancers." (PMID 31075885, 2019). "Literatures showed that targeting autophagy-related proteins LC3, ATG5, ATG7, SQSTM1, and Akt/mTOR (mammalian target of rapamycin) pathway could regulate autophagy initiation in cancer cells." (PMID 31309361, 2019). "LAM shares several features with cancer, such as estrogen receptor overexpression and dysregulation of the mammalian target of rapamycin (mTOR) pathway, leading to inappropriate proliferation, lymphangiogenesis, angiogenesis, and protease-driven matrix degradation." (PMID 30634951, 2019).